INS (insulin)
Diseases named in the same sentence as INS in open-access papers (continued):
Sharing a sentence is not in itself a finding about the gene and the disease.
Insulin resistance (continued). "Furthermore, a reduction in the body weight might result in a decrease in the insulin level with a subsequent improvement in insulin resistance." (PMID 30631594, 2018). "However, high serum triglyceride and low serum HDL-C levels are closely related to insulin resistance, which appears to occur analogously in the brains of PD patients because a defect in the insulin signaling pathway may contribute to the pathogenesis of PD." (PMID 30130376, 2018). "Insulin sensitivity was improved at systemic, epididymal, and inguinal adipose tissues levels in trained rats thus indicating that despite their effects on adipocyte morphological/metabolic changes, polyphenols at nutritional doses remain less effective than exercise in fighting insulin resistance." (PMID 29849911, 2018). "Whether insulin resistance is a cause or consequence of AD is still not clear; however, insulin action has been shown to play a role in several important parts of the progressive pathogenesis of AD." (PMID 30355995, 2018). "However, despite the fact that insulin resistance was associated with an increased risk of stroke, improving insulin sensitivity through the use of TZD did not always reduce the risk of stroke." (PMID 29368615, 2018). "Hypertrophic adipocytes, which release rather than store FFAs, are linked to insulin resistance, but were decreased by cherry consumption, which could explain the normalization of glucose tolerance, insulin sensitivity, leptinemia and dyslipidaemia." (PMID 30029691, 2018). "Because adipose tissue plays a superior role in the induction of insulin resistance and ceramide accumulation affects the insulin action in other tissues, it seems that studying the role of ceramide accumulation in different fat depots on insulin sensitivity is important." (PMID 30545025, 2018). "Reciprocal causation of insulin resistance, obesity, and inflammation indicates that inflammatory factors, chemokines, and immunocytes could reduce insulin sensitivity directly or indirectly, participating in the occurrence and development of insulin resistance." (PMID 30112394, 2018). "The mTORC1 pathway remained activated during high insulin conditions and cell culture experiments, despite insulin resistance, indicating mTORC1 activation may function as an intact signal to suppress formation of autophagosomes, even during high lipid conditions." (PMID 30047243, 2018). "In addition, reduced adiponectin may also result in insulin resistance in insulin sensitivity organs, including liver and fat." (PMID 30390669, 2018). "However, subsequent studies have found no direct association between SHBG and insulin or insulin resistance." (PMID 30057912, 2018). "This study is a proof-of-concept showing that improving insulin signaling and bioenergetics can improve neuronal function, at variance with results from previous studies that described the negative impact on neuronal function of a high-fat diet-induced insulin resistance." (PMID 30235271, 2018). "Besides insulin secretion, high intakes of animal protein may induce insulin resistance through 3-Hydroxyinsbutyrate (a valine metabolite) and fibroblast growth factor 2128." (PMID 29549240, 2018). "Interestingly, there was a positive link between CB adiponectin and insulin/insulin resistance in male offspring, which appears paradox compared with the adult situation, where adiponectin levels usually decline with increasing insulin resistance." (PMID 30355290, 2018). "Additionally, it is well-known that sensitivity of skeletal muscle cells to insulin is deteriorated (insulin resistance) in the patients with type II diabetes resulting in downregulation of intracellular glucose uptake and postprandial increase of blood glucose." (PMID 29872751, 2018).
Insulin resistance (continued). "Moreover, the results of this survey demonstrated that insulin resistance and serum insulin levels decreased significantly in obese women after a period of aerobic training, demonstrating the positive effects of aerobic exercise on improving insulin-dependent indices in obesity." (PMID 30894898, 2018). "Inflammatory factors may directly inhibit insulin signaling and thus induce insulin resistance." (PMID 29737494, 2018). "However, HFD-fed MKO mice showed lower fasting glucose and insulin levels and, therefore, improved insulin resistance as determined by homeostatic model assessment for insulin resistance (HOMA-IR), indicating that deletion of Lmna in macrophages improves obesity-induced systemic insulin resistance." (PMID 29731750, 2018). "In accordance with this hypothesis, either obesity or the intake of an obesogenic, hypercaloric diet enhances β-cell insulin secretion and/or reduces its degradation, promoting hyperinsulinemia, which chronically results in insulin resistance and therefore hyperglycemia." (PMID 30116154, 2018). "Thus the decrease in Arhgap39/Porf-2 could be a result of increased suppression by insulin in the prediabetic state, although later, as insulin resistance with hyperinsulinemia advances to frank diabetes, Arhgap39/Porf-2 levels can be anticipated to rise." (PMID 30406180, 2018). "Although HA were older, they had higher insulin sensitivity and lower insulin resistance and so these associations previously discussed were not seen in them, suggesting that there are other factors that may have a protective role in HA." (PMID 32153911, 2018). "In addition to FFAs release, adipose-tissue-infiltrating bone-marrow-derived cells differentiate into proinflammatory M1-type macrophages that release adipokines and chemokines to contribute to systemic insulin resistance, as exemplified by the suppressive effect of TNFα on insulin signaling." (PMID 30314283, 2018). "These investigations suggest that reduced expression of KLF4 triggered by a high-fat diet in our mouse model (IR+/-IRS1+/-ApoE-/-) may mediate down-regulation of IRS2 and TSC2 expression thereby impairing insulin signaling in adipocytes and promoting insulin resistance." (PMID 30240435, 2018). "Given that insulin binds to receptors expressed on neurons in areas of reward processing, central insulin resistance may contribute to impaired reward signalling and a reduction in insulin resistance may help to normalize the reward response." (PMID 30445718, 2018). "One interpretation of this seemingly paradoxical outcome is that rapamycin promotes long life despite also developing glucose intolerance, insulin resistance and/or decline in insulin production and that preventing these metabolic defects may extend lifespan further still." (PMID 29579736, 2018). "These cytokines could also promote insulin resistance by antagonizing insulin signaling." (PMID 30298053, 2018). "Therefore, as already observed in other models, an insulin resistance state, induced by lipotoxicity, could impair insulin-mediated GLP-1 secretion in L-cells." (PMID 30487448, 2018). "Elder people often have the HOMA-IR (overnight fasting insulin to glucose ratio) level higher than 1, which is diagnosed as insulin resistance (IR); however, it may result from simultaneously increased level of insulin and decreased level of glucose and is not equivalent with type 2 diabetes." (PMID 30186533, 2018). "Furthermore, it was reported that UII could reduce insulin secretion in response to glucose and arginine in the perfused rat pancreas, thereby, potentially contributing to a defective insulin secretion and/or aggravated insulin resistance in DM." (PMID 30442870, 2018). "Insulin is a growth factor, which stimulates cell mitosis and migration, and inhibits apoptosis, effects that could potentially become exacerbated under conditions of insulin resistance and impairment of insulin-regulated metabolic pathways, as seen in T2D." (PMID 30002281, 2018).
Insulin resistance (continued). "Hepatic insulin resistance results in the elevation of hepatic glucose production and triglyceride (TG) accumulation by impairing insulin-mediated inhibition of gluconeogenesis and regulating insulin-mediated TG metabolism, respectively, which contributes to hyperglycemia and dyslipidemia." (PMID 29570673, 2018). "Similarly, treatment of HF-fed wild-type mice with exenatide, a long-acting glucagon-like peptide-1 receptor agonist that stimulates insulin secretion, prevented diet-induced insulin resistance and altered metabolism by restoring hepatic CEACAM1 expression via a PPARγ-dependent pathway." (PMID 30314283, 2018). "The serum insulin of rat after HFD/DEX treatment was distinctly higher than that of normal rat, and the HOMA-IR (homeostasis model assessment index for insulin resistance) of the former was also higher than the latter, suggesting that HFD/DEX caused severe insulin resistance." (PMID 30583568, 2018). "Furthermore, insulin resistance exacerbates inflammatory-related diseases such as hepatitis-C infection whereas administration of TNF-α inhibitors in patients with rheumatoid arthritis increased their insulin sensitivity." (PMID 30538987, 2018). "Increased levels of ROS may disrupt insulin signaling and result in insulin resistance." (PMID 30201694, 2018). "Skeletal muscle represents the largest insulin-responsive tissue in the body and a defect in insulin signaling in muscle critically contributes to the mounting glycemic burden evident with prolonged insulin resistance, eventually resulting in frank type 2 diabetes." (PMID 30071599, 2018). "Insulin ability to induce glucose uptake is in part mediated by the regulation of the vascular tone, and it is likely that interferences in this mechanism could account for a propensity to insulin resistance." (PMID 29342195, 2018). "Since HGF stimulates insulin secretion and increases β-cell mass, both in vitro and in vivo, and due to the fact that increased circulating levels of this hormone are associated with obesity, HGF might link insulin resistance and β-cell hyperplasia." (PMID 30214428, 2018). "However, insulin resistance may be overtaken by high levels of insulin resulting from excess glucose supply in G80 and G100." (PMID 30405429, 2018). "Therefore, the amelioration of inflammation and insulin resistance by SXT in liver of T2DM rats might contribute to activate insulin signaling cascades in skeletal muscle, which accounted for more than 80% of insulin induced glucose disposal in humans." (PMID 30210342, 2018). "Moreover, we assessed the effect of metformin on the metabolic disturbances induced by olanzapine and found that metformin remarkably reversed olanzapine-induced fasting insulin elevation and insulin resistance (both p < 0.001), which was consistent with previous studies." (PMID 29713286, 2018). "The present study suggested that CARD9 knockout may potentially ameliorate diet‐induced inflammation, insulin resistance, metabolic disorders and T2D either by inhibiting the NF‐κB and MAPKs signalling pathway or by improving insulin action and enhancing the energy metabolism." (PMID 29575791, 2018). "Furthermore, information of more precise surrogates for insulin resistance (such as fasting insulin, HOMA-IR, and insulin sensitivity index) and glycaemia markers (such as fasting glucose) were not available in the study, thus, random insulin and glucose levels were used as covariates in our models." (PMID 29321603, 2018). "The insulin resistance secondary to GH excess is generally compensated by the increased insulin secretion from the β-cell, while abnormal glucose tolerance may develop when insulin secretion declines." (PMID 30034367, 2018). "Indeed, insulin resistance is a crucial contributor to the adverse effects on hippocampal cognitive function, and the literature consistently shows many examples that support the positive effects of insulin on cognitive function in rodent models." (PMID 29743868, 2018).
Insulin resistance (continued). "However, patients with diabetes exhibit increased synovial levels of TNF-α and macrophages, suggesting that insulin resistance may impair the protective effect of insulin in the joint, and greater insulin resistance is related to lower femoral neck strength." (PMID 29527173, 2018). "Although insulin sensitizers could be an option for the treatment of uncontrolled T1DM, their possible adverse effects such as weight gain, bone loss, and congestive heart failure encourage further effort to develop new strategy for insulin resistance." (PMID 30445954, 2018). "Furthermore, the levels of HOMR-IR and HOMR-ISI in three groups suggested that XXT could significantly improve insulin sensitivity and insulin resistance." (PMID 29487347, 2018). "Also, a reduction in β-cells insulin production explains the development of insulin resistance." (PMID 29503615, 2018). "Also, vit D may upregulate adiponectin secretion from adipocytes concomitantly with increasing GLUT-4 receptor expression, an important insulin-regulated glucose transporter in myocytes, improving insulin resistance." (PMID 29641459, 2018). "Thus, to understand the effect of insulin resistance on osteocalcin gene expression, time-course experiments were performed in normal and insulin resistant MG-63 osteoblasts, either untreated or treated with 10 nM insulin for different exposure times (15 min; 6, 24, 48 h)." (PMID 28866834, 2018). "In addition to being adaptor proteins that act as negative regulators of cytokine and growth factor signaling, the proteins of the suppressor of cytokine signaling (SOCS), in particular SOCS1 and SOCS3, negatively regulate the insulin signaling, linking the cytokine signaling to insulin resistance." (PMID 29535681, 2018). "Furthermore, despite nonsignificant changes in Matsuda index, the magnitude of the improvement was clinically meaningful among participants in the HP‐diet group, where the Matsuda index increased from 4.6 (borderline insulin resistance) to 11.6 (insulin sensitive)." (PMID 30156033, 2018). "However, some of the inhibitory mechanisms on these nodes can be altered in pathophysiological conditions, participating in the development of insulin resistance and, in turn, contributing to the metabolic abnormalities in insulin-sensitive cell types, namely adipocytes, hepatocytes, and myocytes." (PMID 29535681, 2018). "Moreover, glucose-to-insulin ratio was lower in LBW newborns when compared with NBW infants (33.91 ± 45.17 versus 37.67 ± 62.67; P > 0.01), and homeostasis model assessment of insulin resistance (HOMA-IR) suggests that LBW infants were more insulin sensitive than NBW infants." (PMID 29850608, 2018). "Moreover, it has been recently demonstrated that mice overexpressing TCF7L2 display reciprocal phenotypes, including increased plasma insulin levels, and glucose intolerance due to peripheral insulin resistance, indicating that overexpression of TCF7L2 leads to a phenotype of T2DM." (PMID 29736187, 2018). "Insulin differentially regulates AT and skeletal muscle SIRT1 expression in the short-term and circulating FFA elevation negates these effects, which may be associated with lipid-induced insulin resistance." (PMID 29417372, 2018). "It is caused by the absence of insulin secretion due to either the progressive or marked inability of the β-Langerhans islet cells of the pancreas to produce insulin or due to defects in insulin uptake in the peripheral tissue (insulin resistance)." (PMID 30545361, 2018). "To test whether inhibition of oxidant production from complex II using TTFA and malonate could overcome insulin resistance we assessed insulin-stimulated HA-GLUT4 translocation in 3T3-L1 insulin-resistant adipocytes in the presence or absence of these complex II inhibitors." (PMID 29402381, 2018).
Insulin resistance (continued). "Moreover, there is some evidence that indicates free fatty acids provide the link between obesity and insulin resistance/type 2 diabetes and the free fatty acids may impair insulin-stimulated glucose uptake." (PMID 29766146, 2018). "Mechanistically, hepatic insulin resistance is known to dysregulate lipid metabolism, leading to lipolysis, which then leads to increased production of toxic lipids such as ceramides that have been reported to impair insulin signaling and mitochondrial function." (PMID 30235271, 2018). "An alternative mechanism involves abnormalities in peptic hormones that regulate gastric motility, insulin resistance in cirrhosis that may lead to postprandial hyperglycaemia, high insulin and low ghrelin levels, and abnormalities that are associated with delayed gastric emptying." (PMID 28584525, 2017). "Since insulin-responsive cells upregulate Nox and iNOS expression and the resultant formation of nitric oxide, peroxynitrite, and hydrogen peroxide under conditions relevant to insulin resistance (Sections 4 and 5), singlet oxygen should be generated under such circumstances." (PMID 29081894, 2017). "Although obesity is the strongest risk factor for type 2 diabetes and insulin resistance, not all obese individuals are insulin resistant and many with diabetes are not obese, illustrating the complexity of adipose tissue biology and its relationship with metabolic dysfunction." (PMID 28165007, 2017). "Using a mouse liver cell line, it was also shown that palmitate is an inducer of IL-1β, which could suppress the insulin-induced Akt phosphorylation, suggesting the development of insulin resistance by FFA through the mediation of ROS and inflammatory signaling via the NLPR3 inflammasome." (PMID 28750629, 2017). "However, findings from a nonrandomized study in 73 nondiabetic subjects demonstrated that participants receiving allopurinol for 3 months had significantly lower FPG, fasting insulin, and homeostatic model assessment of insulin resistance (HOMA-IR) than participants in the control group." (PMID 29214183, 2017). "Chronic feeding on a HCD caused insulin resistance in control mice as glycemia and insulinemia were higher in HCD- compared with STD-fed Ptprg+/+ mice; noteworthy, in both feeding contexts circulating glucose and insulin levels were significantly reduced in Ptprg−/− compared with Ptprg+/+ mice." (PMID 29180649, 2017). "Furthermore, it is reported that Baduanjin exercises could improve living quality of patients with T2DM through increasing the sensitivity of body to insulin and decreasing the insulin resistance (IR) index of the body." (PMID 29234435, 2017). "Thus, we consider that the effects of hSeP- and AE2 administration on insulin resistance and insulin secretion, at least in part, might be related to differences in basal blood glucose in this experimental model." (PMID 29162828, 2017). "An analysis of the insulin signaling pathway, including glycolysis and gluconeogenesis, showed that a high dietary arginine level (2.70%) resulted in the upregulation of S6K1 and inhibition of IRS-1, PI3K and Akt mRNA levels, which caused insulin resistance and elevated plasma glucose content." (PMID 28801592, 2017). "Insulin resistance may compromise the ability of insulin to regulate glucose metabolism." (PMID 28133479, 2017). "In the beginning, peripheral insulin resistance could be overcome by increased insulin secretion." (PMID 29152121, 2017). "T2DM is characterised by β-cell dysfunction and insulin resistance, and glucotoxicity and lipotoxicity, which are effects of elevated glucose and free fatty acids on β-cell mass and function, have been proved to have deleterious effect on both β-cell function and insulin action." (PMID 28539618, 2017).